GLI1 (GLI family zinc finger 1)
Diseases named in the same sentence as GLI1 in open-access papers (continued):
Sharing a sentence is not in itself a finding about the gene and the disease.
tumor (continued). "Inversely, the loss of Gli-1 function diminishes IL-6 signaling from tumor-associated fibroblasts, which prevents progression of pancreatic precursor lesions to advanced stages." (PMID 26716648, 2016). "Following the loss of one Ptch1 allele, Gli1 expression increased significantly in tumour tissue, whereas the effect in normal mucosa was less pronounced, probably reflecting background Hh activity in homeostasis." (PMID 27492255, 2016). "Tumor sphere formation and the expression of stemness-related molecules are promoted by ECs through glioma associated oncogene homologue 1 (GLI1) enhancement and its translocation from the cytoplasm to the nucleus." (PMID 26977157, 2016). "While Inhibition of Gli1 in tumor cells reduced Bid levels and its association with RPA-ATRIP complex leading to abrogation of ATR-mediated Chk1 phosphorylation." (PMID 26988232, 2016). "The number of carcinoma specimens and the percentage of tumor cells displaying nuclear GLI1 expression were significantly associated with the tumor grade." (PMID 26843616, 2016). "With the exception of Gli-1, all other pathway members were significantly correlated with the size of the tumor, and Smo was associated with lymph node involvement." (PMID 26389956, 2015). "While both cohorts of mice displayed the common features of advanced PDAC, loss of GLI1 was associated with decreased survival and increased tumor burden." (PMID 25352983, 2014). "The individual members of hedgehog signaling, Shh, Gli1, and Smoothened, were found to correlate with increased metastasis and tumor grade while, at the same time, Gli1 expression was inversely associated with ER." (PMID 23533807, 2013). "In our analysis, the tumor that harbored the PTCH1 P681L mutation expressed GLI1 at a level that was greater than six standard deviations above the mean, and was therefore clearly an outlier." (PMID 24368541, 2013). "The irradiated tumor cells with higher Shh and Gli1 expression were associated with stronger tumor cell repopulation." (PMID 23762282, 2013). "We conclude that the ability of this integrin to activate FAK and the consequent activation of Ras and induction of GLI1 expression underlie its contribution to tumour initiation." (PMID 23436775, 2013). "The universal Hh target Gli1 is expressed in Ptc1 deleted tumours as well as in those with additional loss of RBP-J, as is Hes1, a target of both the Hh and Notch pathways." (PMID 20950430, 2010). "As anticipated, the expression of all Gli1 variants was remarkably upregulated in the tumor samples compared to normal cerebellum, but the relative expression pattern of the variants was not apparently influenced by tumorigenesis." (PMID 20433698, 2010). "Increased levels of nuclear GLI1 expression in human tumourous breast tissues show a significant association towards lower overall survival outcome and a more aggressive tumour phenotype." (PMID 19706168, 2009). "Furthermore, ADAR1 induces an arginine to glycine (R701G) mutation in hepatic CSCs through its regulation of RNA editing on the glioma‐associated oncogene homolog 1 (GLI1), which improves the nuclear localisation of GLI1 and promotes tumour initiation." (PMID 40665579, 2025). "Additionally, the association between GLI1 expression and immune infiltration within the tumor immune microenvironment (TMIE) was examined." (PMID 39483334, 2024). "Ultimately, if a tumor is suspected to harbor a pathologic GLI1 gene alteration, molecular analysis should be performed to ascertain the underlying genetic defect and prove the presence of GLI1 gene fusion." (PMID 39720383, 2024). "Therefore, we concluded that Gli1+ CPs were the targets of this anti-tumor drug and that their loss was the cause of the iatrogenic adverse effect on the growth plate." (PMID 38409269, 2024).
tumor (continued). "Glioma-associated oncogene 1 (GLI1) transcription factor is expressed as a result of Sonic hedgehog pathway activation, the dysregulation of which contributes to tumorigenesis in several tumor types." (PMID 39062853, 2024). "Therefore, our data of identifying reduced atypical Myc+ basal cells in PIN tissues of HiMyc-ARKO mice implicate an underlying mechanism by which stromal AR deletion in Gli1-lineage cells impairs prostatic oncogenesis and tumor development." (PMID 36323713, 2022). "Interestingly, the R100 and S105 residues that we identified as being important for SUFU binding from scanning human tumor-derived GLI1 mutations were also extremely well-conserved in all chordate and all invertebrate species that we examined, as was L106." (PMID 35831023, 2022). "Upregulation of Gli1 in tumor group was significantly associated with the late stage of GC." (PMID 34350176, 2021). "Similarly, high levels of GLI1 were associated with a higher incidence of tumor relapse in CRC patients who underwent 5-FU based chemotherapy." (PMID 34638233, 2021). "Some studies showed that Gli1 is linked to tumor resistance, whereas others suggested that Gli2, rather than Gli1, may be more predictive of resistance." (PMID 35059317, 2021). "Additionally, high expression of both p-AKT and GLI1 was significantly associated with the following clinicopathological factors: tumor size, lymph node metastasis, invasion depth, venous invasion, degree of differentiation, and TNM staging." (PMID 34572373, 2021). "GLI1 inhibition in a murine BRAFV600E variant xenograft model of CRC resulted in the same down-regulation of NBS1 observed in vitro as well as significant reduction of tumor growth/burden." (PMID 32185127, 2020). "Thus, elevated expression of GLI1 appears to predict tumor response to chemotherapy and is associated with poor prognosis in EAC." (PMID 32913560, 2020). "High levels of Gli1 expression was significantly associated with patients with tumors in the body and tail of pancreas (p = 0.006), patients with poorly differentiated tumor tissues (p = 0.001), and patients grouped into the T3-4 category of UICC classification (p = 0.026)." (PMID 31417657, 2019). "We investigated whether interleukin (IL)-24, a tumor suppressor, inhibits GLI1 and the associated DDR pathway in human NSCLCs." (PMID 31783569, 2019). "In addition, arsenic trioxide (ATO), an approved FDA drug, was shown to bind and inhibit GLI1, causing reduced tumour cell growth in vitro and in vivo." (PMID 30068568, 2018). "Since all patients underwent chemotherapy (containing 5-FU), this correlation further support our hypothesis that high expression of GLI1/GLI3 molecules in the tumor indicates poor outcomes from 5-FU associated chemotherapy treatment." (PMID 28413604, 2017). "Our expression studies using mouse tumor sections raise the question of whether the genes encoding any of the HH ligands and GLI1 are increased in a subset of human PCa." (PMID 27935821, 2017). "GLI1 overexpression is associated with clinical staging of tumor and tumor recurrence of OSCC." (PMID 28708091, 2017). "Furthermore, the GEO database search (GSE10245) showed a positive association between Set7 and Gli1 in NSCLC tumor samples, suggesting the involvement of this Set7-Gli3-Gli1 axis in the development of NSCLCs." (PMID 27146893, 2016). "Overexpression of CD44, Shh, and Gli1 protein was significantly associated with larger tumour size, aggressive gross type, and less differentiated tumour histological type, all of which were clinicopathological features associated with a high metastatic potential." (PMID 26839535, 2016). "This gene was then named after the tumor, i.e. glioma-associated oncogene homolog 1 (GLI1)." (PMID 26053182, 2015). "Moreover, SHH and GLI-1 expression were also up-regulated in tumor-associated stromal cells in PC tissue specimens." (PMID 25682877, 2015).
tumor (continued). "This indicates that as PDAC progresses, lower GLI1 levels may actually prime tumor cells towards an EMT program, which would be associated with metastasis and advanced stages of the disease." (PMID 25352983, 2014). "Other studies have also implicated GLI1 in the function of tumour stem or initiating cells." (PMID 23436775, 2013). "Tumours in heterozygous Ptch1 mice exhibited elevated transcript levels of Gli1 and Ptch1 itself, indicating that abnormal Hedgehog signalling may be common to the various tumours associated with Gorlin's syndrome." (PMID 22550422, 2012). "Additionally, tumor initiating cells in some cancers have been shown to be dependent on sustained Hh induced signaling and subsequent activation of Gli1 resulting from ligand over-expression or mutational activation of the Hh pathway." (PMID 22140510, 2011). "Moreover, reports on gli1 acting independently of the Hh-signaling pathway (i.e. in a non-canonical fashion) are few in vertebrates and are most often associated with tumor environments." (PMID 21203590, 2010). "However associations between GLI1 overexpression and lymph node status as well as histological grade of the tumours as stated by univariate analysis were multivariate insignificant." (PMID 19706168, 2009). "Additionally in human oesophageal squamous cell carcinomas an association was found between the expression of GLI1 and depth of tumour invasion, status of lymph node metastasis, as well as unfavourable overall survival." (PMID 19706168, 2009). "Furthermore, a greater histological grade of the tumour was associated with overexpression of GLI1, GLI2, PTCH1 and SMO, which may indicate a critical function for Hh signalling in HNSCC malignancy." (PMID 39234399, 2024). "Besides the lack of mutations on Hh pathway components in GBMs, it has been shown that the glioma-associated oncogene homolog 1 (GLI1) zinc-finger transcription factors, terminal effectors of the Hh pathway, presents two tumor-specific splicing isoforms, which directly influences tumor malignancy." (PMID 34178638, 2021). "Glioma-Associated Oncogene Homolog 1 (GLI1) is the key transcription factor of the Hedgehog pathway, while abnormal activation of GLI1 can activate the expression of multiple downstream targets, affecting tumor cell proliferation, apoptosis, DNA damage and repair (DDR), and other processes." (PMID 34659557, 2021). "GLI1 repression may also explain why engraftment and growth of Ptch+/− derived tumors were blocked by bFGF, as this likely caused repression of GLI1 activity in a susceptible phase of tumor growth." (PMID 31835472, 2019). "Moreover, our study revealed that the driver genes mutation of tumor cell might program the tumor microenvironment, and the expressions of Shh and Gli1 were found to be related to the status of SMAD4/DPC4." (PMID 31417657, 2019). "In addition, GLI1/2 inhibitors may also be effective in tumours harbouring activating mutations in SMO, or downstream mutations in the HH pathway, as well as in tumours that have acquired resistance to SMO inhibitors." (PMID 30068568, 2018). "Hence, we postulate that GLI1 activity may change during tumor progression and this could be related to acquisition of new mutations that regulate GLI1 activity." (PMID 29137400, 2017). "The interplay between ROS and GLI1 signaling not only affects tumor cell survival but also influences the TME, promoting angiogenesis and immune evasion." (PMID 41596413, 2026). "In conclusion, our work establishes STK38 as a central coordinator of cellular plasticity and intratumoral heterogeneity in pRCC, and identifies GLI1 inhibition as a promising means of disrupting oncogenic self-renewal programs in aggressive tumor subsets." (PMID 41540036, 2026). "The formation of ROS triggers the activation of GLI1 signaling and regulates the proliferation and apoptosis of tumor cells." (PMID 41596413, 2026).
tumor (continued). "The covariates included in the model were the promoter methylation levels of the NUPR1, NDRG2, and GLI1 genes, as well as age and tumor size." (PMID 41596413, 2026). "While Hh-targeted therapies have an anti-fibrotic role and reduce myCAFs (Gli1+ stromal cells), they simultaneously encourage aggressive mesenchymal tumor cell features." (PMID 40508010, 2025). "The second tumor type harboring the MALAT1::GLI1 fusion is gastroblastoma, which presents with markedly different characteristics." (PMID 39851545, 2025). "Methylation of the promoter region of GLI1, a crucial transcription factor in the SHH pathway, is reduced by H. pylori in an m6A‐dependent manner, leading to increased GLI1 expression and enhanced tumor proliferation." (PMID 40231893, 2025). "This case contributes to the growing body of literature on GLI1-altered neoplasms, emphasising the need for further molecular and clinical characterisation to refine prognostic tools that would aid in clinical decision making." (PMID 41035732, 2025). "On imaging, GLI1-rearranged enteric tumors usually appear as clearly demarcated neoplasms arising from the affected segment of the gastrointestinal wall." (PMID 39851545, 2025). "Further analysis of tumor samples also revealed prevalent reductions in the mRNA expression of multiple Gli1 target genes in D1SP-treated tumors compared with controls." (PMID 39748059, 2025). "In a xenograft tumour mouse model, tumour growth and monocyte infiltration were inhibited in GLI1 or CCL20 knockout PLC5 cells." (PMID 40913253, 2025). "The GLI1 expression in tumor tissue of tumor-bearing mice reduced by twofold, when treated with 1 mg/kg bodyweight of rolipram, and by sixfold, when treated with 5 mg/kg bodyweight of rolipram." (PMID 39880092, 2025). "The diagnostic application of GLI1, as well p16 immunohistochemical staining, was analyzed in a cohort of GLI1-altered neoplasms, comprising equal numbers of GLI1-amplified and GLI1-rearranged tumors." (PMID 39851545, 2025). "mRNA levels of GLI1 or CCL20 were found to be significantly elevated in tumour tissues compared to paired adjacent non‐tumour liver tissues." (PMID 40913253, 2025). "At the end of the animal experiment, the mice were sacrificed, and tumours bearing GLI1 KO or CCL20 KO cells exhibited reduced size and weight relative to WT controls." (PMID 40913253, 2025). "Histopathological analysis revealed a mesenchymal tumour harbouring a novel NCOR2(exon 7)::GLI1(exon 6) gene fusion." (PMID 41035732, 2025). "This Gal-1/β1 integrin/Gli1 axis represents a central pathway through which Gal-1 orchestrates tumor cell plasticity, migration, and metastatic potential." (PMID 40710343, 2025). "Tumour growth in mice was inhibited in mice implanted with GLI1 KO or CCL20 KO cells compared to those with WT cells." (PMID 40913253, 2025). "Glioma-associated oncogenes (GLIs) consist of three members: GLI1, GLI2, and GLI3, which are the downstream transcription factors involved in mediating the signaling pathway and leading to tumor progression." (PMID 40133270, 2025). "During the study, p-AKT, p-S6K1, and GLI1 expression levels decreased in tumor cells after NLRP3 knockdown." (PMID 39744485, 2025). "Protein expression demonstrated upregulation of the Hh pathway in mBCC tumours including GLI1 and GLI2, whereas nodBCC had a normal level of expression of the Hh pathway, not above the levels of physiological activation." (PMID 41373535, 2025). "Conversely, tumor volume and mass significantly increased in the Lv‐miR‐217 + oe‐GLI1 group compared to the Lv‐miR‐217 + oe‐NC group." (PMID 40909350, 2025).
tumor (continued). "Conversely, mSWI/SNF derived subunit SMARCB1 was detected to suppress tumor growth and enhance the oncological therapeutic response in in vivo studies by inducing epigenetic modifications in the GLI-1 and EGFR genetic sequences." (PMID 39971779, 2025). "GLI1 overexpression showed remarkable changes in the composition of the immune cell compartment, accompanied by a slight increase in tumor growth." (PMID 39090759, 2024). "In chondrosarcoma xenograft tumors, saridegib inhibited GLI1 expression and significantly reduced tumor volume in mice." (PMID 38612911, 2024). "This latest, is often characterized by activation of Sonic Hedgehog (SHH) signalling, with overexpression of Gli1 and Gli2 that are responsible for the generation of an immunosuppressive tumour microenvironment." (PMID 38886736, 2024). "On the other hand, we found GLI1 phosphorylated (pGLI1) in tumor and stroma tissues where the expression was observed mainly in Gleason 7 (4 + 3) and 9 (4 + 5) (grade groups 3 and 5 respectively)." (PMID 38370352, 2024). "We validated that EHF promotes the migration and infiltration of TAMs into tumors through the CCL2/CCR2 axis, which complements the function of GLI1 in tumor cells and provides a more comprehensive mechanism for EHF‐mediated cholangiocarcinogenesis." (PMID 38741887, 2024). "Analysis of paired tumor and normal tissue samples from the TCGA database further verified significant expression of GLI1, GLI2, and GLI3 in nine, ten, and ten types of tumors, respectively." (PMID 38498906, 2024). "Potential targeted therapeutic options in GLI1-altered neoplasms include sonic hedgehog signaling pathway inhibitors." (PMID 38491228, 2024). "Analysis of sample data from TCGA and GTEx revealed a significant decrease in GLI1 expression in tumor samples compared to normal tissue samples." (PMID 39483334, 2024). "PS was shown to inhibit the nuclear localization of Gli1 in endothelial and pericyte cells within the tumor microenvironment." (PMID 38794148, 2024). "In order to evaluate the potential of GLI1 as a therapeutic target, we initially examined the expression pattern of GLI1 across various types of cancers, comparing tumor tissues with their corresponding normal tissues." (PMID 39483334, 2024). "Meanwhile, we examined the Hh pathway in tumor xenograft tissues and observed a significant decrease in the levels of the downstream targets of Hh pathway, Gli1 and Gli2." (PMID 38909089, 2024). "Overexpression of Shh in PCa cells can elevate stromal Gli1 expression and accelerate tumor growth in the xenograft tumor model." (PMID 39369165, 2024). "Immunohistochemical staining of clinical samples further confirmed the low expression of GLI1 in tumor tissue." (PMID 39483334, 2024). "The tumor-induced skin expressed mRNA levels of hedgehog genes Gli1, Gli2, and Ptch1 that were 8.1, 4.4, and 3.4 times higher compared to healthy skin (all genes: p < 0.001)." (PMID 38308119, 2024). "Taken together, these results indicate that tumor-derived GLI1 plays an important role in sustaining expansion and recruitment of PMN-MDSCs, in promoting their immunosuppressive phenotype, and in suppressing CD8 + and CD4 + T cell function." (PMID 39090759, 2024). "FOXS1 can inhibit the ubiquitination of GLI1 to upregulate Hedgehog/GLI1 signaling, which leads to tumor metastasis via inducing EMT." (PMID 39092293, 2024). "Consistent with the increased penetrance and severity, the levels of Gli1, Gli2, and Sufu expression were higher in Ptch1–/+;3nSD MB tumor tissues compared with those of the Ptch1–/+ tumors, and the expression was enriched in the nucleus." (PMID 38358805, 2024). "Another crucial aspect in the diagnosis of neoplasms with GLI1 alterations is that while amplification is reliably detected by FISH, rearrangement is typically identified through genomic sequencing (NGS, RNAseq), which is not universally accessible." (PMID 38275873, 2024).